HMGB1 (high mobility group box 1)
Diseases named in the same sentence as HMGB1 in open-access papers (continued):
Sharing a sentence is not in itself a finding about the gene and the disease.
psoriasis (continued). "Additionally, the release of HMGB1 through autophagy in keratinocytes promotes skin inflammation in psoriasis." (PMID 38892253, 2024). "Additionally, HMGB1 treatment can significantly aggravate psoriatic inflammation in imiquimod (IMQ)‐induced mouse psoriasis‐like inflammation, which further indicates that HMGB1 participates in the pathogenesis of psoriasis." (PMID 38414294, 2024). "Interestingly, the mechanism of action of HMGB1 has also been implicated in existing psoriasis drugs, such as methotrexate (MTX), which inhibits the interaction between HMGB1/RAGE by binding to the RAGE binding region of HMGB1." (PMID 38255845, 2024). "HMGB1 has been confirmed to be highly expressed in psoriasis patients' serum and epidermis tissues." (PMID 38414294, 2024). "HMGB1 is involved in psoriasis progression through several mechanisms." (PMID 38255845, 2024). "Importantly, blocking HMGB1 or IL-8 by neutralizing antibodies not only attenuated but also accelerated the recovery from psoriasis-like dermatitis induced by IMQ." (PMID 35075118, 2022). "However, HMGB1 levels in epithelial intercellular spaces in psoriasis were increased more than in controls." (PMID 35053208, 2021). "Moreover, the imiquimod-induced psoriasis mice model was used to check the role of HMGB1 in PV equilibrium in vivo." (PMID 35053208, 2021). "HMGB1 could function as a proinflammatory cytokine; as a result, it contributes to the development of psoriasis-like inflammation." (PMID 35053208, 2021). "Blocking the proinflammatory function of the HMGB1–IL-18 axis may be useful for psoriasis treatment in the future." (PMID 35053208, 2021). "Moreover, recently HMGB1 has been shown to be secreted extracellularly by an autophagy unconventional mechanism in psoriasis by keratinocytes." (PMID 34134693, 2021). "Data demonstrated that blocking HMGB1 is effective in ameliorating psoriasis." (PMID 35053208, 2021). "Evidence suggests that HMGB1 plays a critical role in the pathogenesis of psoriasis, and HMGB1-based therapeutic strategies may be useful in psoriasis." (PMID 28769106, 2017). "Our findings indicate that LXA4 and its analog may be potential therapeutic candidates for psoriasis because of their ability to modulate the translocation and expression of HMGB1." (PMID 28769106, 2017). "It is plausible to speculate that both TLR4 and RAGE may be involved in the HMGB1-induced inflammation in psoriasis." (PMID 28769106, 2017). "Consequently, our study provides convincing evidence that LXA4 and its analog play important roles in suppressing the expression and translocation of HMGB1 in psoriasis." (PMID 28769106, 2017). "HMGB1 may favor the shift of T regulatory cells into Th17 cells, which are crucial players of psoriasis induction." (PMID 29156622, 2017). "HMGB1 has emerged as a promising biomarker in autoimmune and autoinflammatory skin diseases, as accumulating evidence links its disease-specific expression patterns to inflammatory cascades in conditions such as vitiligo, psoriasis, atopic dermatitis, and pemphigus." (PMID 40308590, 2025). "Importantly, current evidence suggests that HMGB1 also contributes to the progression of psoriasis." (PMID 38666958, 2024). "In addition, HMGB1 serum levels were obviously higher in severe patients than those in moderate patients and, more importantly, positively correlated with the index of psoriasis severity degree, which further demonstrates that HMGB1 is involved in the development and progress of psoriasis." (PMID 38414294, 2024). "So, inhibiting HMGB1 may be a candidate idea for the treatment of psoriasis." (PMID 38414294, 2024). "However, whether HMGB1 can regulate Th17 cell differentiation within the pathological environment of psoriasis remains unclear." (PMID 38414294, 2024). "Targeting HMGB1 may be a possible potential candidate for the immunotherapy of psoriasis." (PMID 38414294, 2024). "For this reason, the HMGB1 blockade may represent a new direction in the suppression of psoriasis." (PMID 35053208, 2021).
psoriasis (continued). "High Mobility Group Box 1 (HMGB1) is a pro-inflammatory factor produced by keratinocytes and is highly expressed in psoriasis model mice." (PMID 40362523, 2025). "It has been reported that, in PV patients, increased HMGB1 is secreted from epidermal keratinocytes and some dermal cells and that IMQ induces psoriasis-like inflammation." (PMID 40308590, 2025). "It presents molecular targets such as high-mobility group box-1 (HMGB1), dual-specificity phosphatase-1 (DUSP1), and the aryl hydrocarbon receptor (AhR) for treating psoriasis." (PMID 38892253, 2024). "However, our present study provides further evidence that HMGB1 participates in the pathogenesis of psoriasis, which may exert its regulatory effect on Th17 cell differentiation and IL‐17A production by IL‐23 and TLR4 signaling pathways to amplify its inflammatory effects." (PMID 38414294, 2024). "HMGB1, TLR4, IL‐23, and IL‐17A serum concentrations in psoriasis patients were significantly elevated compared with those in healthy controls (t = 7.716, 2.433, 4.443, and 10.339, respectively, all p < .05 or .01)." (PMID 38414294, 2024). "For example, Hmgb1-KD mice and mice treated with HMGB1 antibodies exhibited improved disease outcomes after IMQ-induced psoriasis modeling." (PMID 38255845, 2024). "The serum levels of HMGB1, TLR4, IL‐23, and IL‐17A in psoriasis patients were significantly higher than healthy controls, especially in severe patients, and positively correlated with the severity index." (PMID 38414294, 2024). "Interestingly, different expression profiles of HMGB1 might point to different types of psoriasis." (PMID 38666958, 2024). "Serum concentration of HMGB1, TLR4, IL‐23, and IL‐17A were all positively correlated with psoriasis patients' PASI (r = 0.66, 0.68, 0.65, and 0.65, respectively, all p < .001)." (PMID 38414294, 2024). "The link between HMGB1 and its receptors stimulates RAGE expression, inducing a Th17 shift in subjects affected by psoriasis and, in turn, sustaining the inflammatory condition." (PMID 35053208, 2021). "High mobility group box 1 (HMGB1) serves as an inflammatory cytokine when secreted extracellularly in psoriatic lesions and is involved in the development of psoriasis." (PMID 28769106, 2017). "In addition, there was also a positive correlation between every two detected indexes among HMGB1, TLR4, IL‐23, and IL‐17A in psoriasis patients." (PMID 38414294, 2024). "High mobility group box 1 (HMGB1) is an important proinflammatory cytokine, which has been confirmed to be highly expressed in the peripheral circulation and epidermis tissues of psoriasis patients." (PMID 38414294, 2024). "In addition, histological analysis of S100A2 and HMGB1 reflects the severity of drug eruption, however, they could not reflect the specificity of drug eruption, because they are increased in other inflammatory skin diseases, such as atopic dermatitis and psoriasis." (PMID 34299145, 2021). "While, in the pathological environment of psoriasis, whether HMGB1 can exert the regulatory effect on IL‐17A is not clear." (PMID 38414294, 2024). "Furthermore, HMGB1 upregulates the expression of TLR2, TLR4, and RAGE in the skin lesion area of psoriasis and activates the inflammasome and NF-κB pathway in keratinocytes to promote IL-18 secretion, which would aggravate the condition of IMQ model psoriasis mice." (PMID 38255845, 2024). "The alarmins HMGB1, IL-33, S100A7, and S100A12 were significantly elevated in the serum of patients, which states the hypothesis that they play specific roles in the immunopathology of psoriasis." (PMID 32377165, 2020).
cognitive decline (21 papers, 2018 to 2025). "As a nuclear protein, HMGB1 plays an important role in the inflammatory process, mediates hippocampal inflammation, and causes cognitive decline." (PMID 33836651, 2021). "HMGB1 plays a pivotal role in cognitive decline where HMGB1 is supposed to caused disruption of the BBB leading to cognitive deficits in aged rats." (PMID 30271319, 2018). "While pathological causes of cognitive decline, such as small vessel disease and neurodegeneration, are also associated with AF, some have speculated that HMGB1 may be responsible for eliciting atrial fibrillation." (PMID 34685561, 2021). "As well as clinical data obtained from patients undergoing gastrointestinal surgery showed that serum HMGB1 and IL-6 levels was elevated post-surgery, and the increased post-operative HMGB1 and IL-6 levels were associated with the cognitive decline the occurs 1-week post-surgery." (PMID 30271319, 2018). "As aberrant astrocyte morphogenesis and gliovascular development may predispose the adult brain to cognitive decline and/or impair vascular responses to neuronal injury, elucidating the role of HMGB1 in gliovascular plasticity may lead to therapies for neuroprotection." (PMID 37587100, 2023). "Inhibition of microglial activation or blockade of high-mobility group box 1 (HMGB1) release can prevent chronic pain–induced cognitive decline." (PMID 41195280, 2025). "The precise mechanism of HMGB1’s participation in cognitive decline is still limited, and more research is needed." (PMID 39466324, 2025). "RAGE plays a crucial role in the pathogenesis of AD by interacting with ligands such as AGEs, Aβ, HMGB1, and S100 proteins, accelerating the aging process and promoting neuroinflammation, synaptic dysfunction, amyloid accumulation, and cognitive decline." (PMID 39796257, 2025). "Additional studies with larger patient populations are needed to validate the utility of HMGB1 as a predictive biomarker for cognitive decline following acute ischemic stroke." (PMID 38708343, 2024). "In WT mice surgery induced significant cognitive decline in the Y-maze test, p = 0.019), microgliosis (p = 0.001), and increases in plasma IL-6 (p = 0.002) and HMGB1 (p = 0.001) when compared to anesthesia alone." (PMID 36927341, 2023). "The following is a description of the results of a series of studies from a single laboratory implicating the role of HMGB1-induced inflammation for the cognitive decline that follows the aseptic trauma of surgery." (PMID 34685561, 2021). "That HMGB1 is itself sufficient for neuroinflammation and cognitive decline was demonstrated by fact that the disulfide form of the HMGB1 antigen produces the same inflammatory and behavioral changes as was seen after surgery." (PMID 34685561, 2021). "Below are therapeutic strategies that can be implemented in the event that the initiating role of HMGB1 for postoperative cognitive decline is established." (PMID 34685561, 2021). "Postoperative cognitive decline, reflected by a decrease in freezing time in the context-sensitive trace-fear conditioning paradigm, was attenuated by anti-HMGB1." (PMID 34685561, 2021). "Cognitive decline was shown to be suppressed by early subcutaneous injection of HMGB1 antibodies in the 5 × FAD mouse model of AD53." (PMID 33514742, 2021). "That HMGB1 is necessary was demonstrated with a neutralizing antibody directed against HMGB1 in which the surgery-induced neuroinflammatory cascade and behavioral changes of cognitive decline were entirely prevented." (PMID 34685561, 2021). "Studies have reported that HMGB1 can mediate systemic inflammatory responses and lead to neuroinflammation and cognitive decline." (PMID 33836651, 2021). "HMGB1 has been implicated in impairing memory via mediating RAGE and TLR4 however, the exact mechanism of HMGB1 in cognitive decline is limited." (PMID 30271319, 2018).
cognitive decline (continued). "Translational implication of HMGB1 will be a paradigm shift, which will not only overcome the limitation of currently available AEDs, improve the cognitive decline as well." (PMID 30271319, 2018). "Administration of endogenous HMGB1 proteins produced cognitive decline in mice and neutralized HMGB1 mAb ameliorated cognitive decline and inhibited the inflammatory response after tibial surgery, suggesting a initiating role for this mediator in POCD." (PMID 30271319, 2018). "Furthermore, the cognitive assessment was only performed at a single time point, which limits the interpretation of the temporal relationship between HMGB1 and cognitive decline." (PMID 38708343, 2024). "This could uncover novel therapeutic targets for pharmacological inhibition of HMGB1 signaling to mitigate cognitive decline." (PMID 38708343, 2024). "Numerous studies have implicated the role of HMGB1-induced inflammatory response in cognitive decline following aseptic surgical trauma, and preclinical studies have demonstrated the alleviation of HMGB1-induced neuroinflammation via the administration of anti-HMGB1 antibodies." (PMID 37892748, 2023). "This scoping review maps evidence on the key roles of AGEs, RAGEs, other ligands such as Leukotriene B4 (LTB4), High-mobility group box 1 (HMGB1) nuclear protein, brain–kidney–muscle crosstalk, alternate pathomechanisms in neurodegeneration, and cognitive decline related to diabetic ischemic stroke." (PMID 36421725, 2022). "This is concerning because increased HMGB1 expression has been found to be a marker of neuroinflammatory conditions and may be a predictor of cognitive decline." (PMID 35411847, 2022). "Yet, as the evidence continues to accrue in the preclinical literature, it is worthwhile to consider the therapeutic strategies that will be needed to mitigate the putative role of HMGB1 in the development of postoperative neuroinflammation and cognitive decline." (PMID 34685561, 2021). "HMGB1 was reportedly responsible for memory impairment in naïve mice, and the administration of anti-HMGB1 antibodies was beneficial for surviving animals by preventing cognitive decline." (PMID 34512319, 2021). "HMGB1 could impair neurite outgrowth in a mouse model of AD and lead to cognitive decline." (PMID 32245271, 2020). "Through suppressing HMGB1, the levels of TNF-α, IL-1β, and IL-6 decreased, and hippocampal atrophy and cognitive decline were attenuated in the CCH model of mice." (PMID 38231472, 2024). "HMGB1 suppression with CRISPR/Cas9 knockout plasmid restored TNF-α, IL-1β, and IL-6 and attenuated hippocampal atrophy and cognitive decline." (PMID 32245271, 2020). "The detailed mechanisms of HMGB1 in mediating cognitive decline at the chronic phase after CCH have not yet been established." (PMID 32245271, 2020). "IL-1 modulation has been implicated to ameliorate LPS-induced cognitive dysfunction, however, IL-1 blockade ameliorated cognitive decline by reducing microglia without affecting HMGB1." (PMID 30271319, 2018). "Moreover, HMGB1 suppression could decrease proinflammatory cytokines (TNF-α, IL-1β, and IL-6), attenuate hippocampal atrophy, and improve cognitive decline." (PMID 32245271, 2020). "Moreover, HMGB1 as a common biomarker of TBI, neuroinflammation, epileptogenesis and cognitive decline might be instrumental in assessing the disease progression, early prediction of disease as well as evaluating patient’s response to therapy." (PMID 30271319, 2018).
coronary artery disease (21 papers, 2012 to 2024). "A growing body of evidence has indicated the important role of HMGB-1 in plaque formation, rupture, and thrombosis, which are all pathogenic phenomenons in coronary artery disease." (PMID 27847406, 2016). "One limitation of our study was the lack of follow-up data in the study groups, which limited the value of serum HMGB1 in risk stratification and prognosis in patients with coronary artery disease." (PMID 23935732, 2013). "Our study demonstrates for the first time an association between CTA plaque characteristics and HMGB1 expression in patients with stable coronary artery disease." (PMID 23284878, 2012). "Interestingly, serum HMGB1 levels have also been found to be independently associated with coronary artery disease and carotid plaque susceptibility in diabetic populations." (PMID 38481996, 2024). "In this study, we sought to investigate the association of plasma HMGB1 with coronary plaque composition in patients with suspected or known coronary artery disease (CAD)." (PMID 23284878, 2012). "HMGB1, for example, has been investigated in subclinical coronary artery disease (CAD) where a potentiating inflammatory effect was attributed to the alarmin in the acute phase of ischemic injury." (PMID 36232476, 2022). "In univariable analysis for identifying predictors of composite of morbidity endpoints, post-CPB HMGB1 concentrations, coronary artery disease, congestive heart failure, EuroSCORE II, pre-operative creatinine, and duration of CPB exhibited p < 0.05." (PMID 32286371, 2020). "In the present study, we evaluated serum HMGB1 levels in different types of coronary artery disease and identified that serum HMGB1 levels were higher in all types of coronary artery disease than in the controls." (PMID 23935732, 2013). "Serum HMGB1 levels in the patients with coronary artery disease were higher compared with those in healthy volunteers (63.5±15.29 vs. 21.98±4.33 μg/l; P<0.01)." (PMID 23935732, 2013). "Further studies are required to ascertain the predictive value of serum HMGB1 in patients with coronary artery disease." (PMID 23935732, 2013). "Serum HMGB1 levels in patients with coronary artery disease were higher compared with those in healthy volunteers (63.5±15.29 vs. 21.98±4.33 μg/l; P<0.01)." (PMID 23935732, 2013). "High mobility group box 1 protein (HMGB1) has been identified as a novel pro-inflammatory cytokine in coronary artery disease." (PMID 23226786, 2012). "HMGB1 levels are positively correlated with CRP levels in coronary artery disease patients." (PMID 30501043, 2018). "Additionally, we identified that serum HMGB1 is positively correlated with cTnI in patients with coronary artery disease." (PMID 23935732, 2013). "Therefore, it is necessary to clarify the role of HMGB1 in the process and development of various types of coronary artery disease." (PMID 23935732, 2013). "The current findings suggest that serum HMGB1 may be used for evaluation of severity and stratification of coronary artery disease." (PMID 23935732, 2013). "However, our preliminary results demonstrated significant positive results, which suggest a role of HMGB1 in coronary artery disease." (PMID 23935732, 2013). "Moreover, HMGB1 levels correlate with the severity of coronary artery disease." (PMID 34044825, 2021). "In addition, clinical studies showed elevated circulating HMGB-1 in coronary artery disease." (PMID 27847406, 2016). "Apart from the great knowledge we already have about the role of HMGB1 as a danger signal, further research is required to solve the disagreement whether HMGB1 is deleterious or beneficial in ischemic heart diseases and how this can be implemented in the clinic." (PMID 24363498, 2013). "The aim of this study was to evaluate the correlation between levels of serum high-mobility group box-1 (HMGB1) and high-sensitivity C-reactive protein (hs-CRP) and cardiac troponin I in patients with coronary artery disease." (PMID 23935732, 2013).